VEGFA (vascular endothelial growth factor A)
Diseases named in the same sentence as VEGFA in open-access papers (continued):
Sharing a sentence is not in itself a finding about the gene and the disease.
Parkinson disease (44 papers, 2010 to 2026). A progressive degenerative disorder of the central nervous system characterized by loss of dopamine producing neurons in the substantia nigra and the presence of Lewy bodies in the substantia nigra and locus coeruleus. "VEGFA has been proposed as a plausible gene therapy for Parkinson’s disease patients because of its role in the nervous system." (PMID 36591016, 2022). "The ALT-like type was enriched for NABA ECM-affiliated pathways and regulation of lymphocyte activation, and the NDTMM type was enriched for Parkinson’s disease, neutrophil degranulation, and vascular endothelial growth factor-alpha (VEGFA) signaling pathways." (PMID 36359738, 2022).
Ascites (43 papers, 2008 to 2025). Accumulation of fluid in the peritoneal cavity (between the layers of the peritoneum that lines the abdomen). "In comparison, in a large study of patients with ascites caused by different pathological conditions (n = 1012), mean VEGFA values of 676 pg/mL and 218 pg/mL were reported in malignant and benign cases, respectively." (PMID 34198773, 2021). "Increase in expression levels of VEGFA-spliced, VEGFA-165 or VEGFA-121 correlated with ascites presence and feeble or absent tumor capsule." (PMID 29888133, 2018).
glomerulosclerosis (43 papers, 2007 to 2025). A hardening of the kidney glomerulus caused by scarring of the blood vessels. "Previous studies have shown that blocking VEGFA‐VEGFR2 signalling with soluble VEGFR1 can accelerate the progression of glomerulosclerosis, loss of PTCs, and interstitial fibrosis." (PMID 40682486, 2025). "In the disease of endothelial hyperplasia, excessive release of VEGFA leads to endothelial cell proliferation and swelling, but too little release of VEGFA will lead to endothelial damage and apoptosis, resulting in glomerulosclerosis." (PMID 36386814, 2022). "In addition, transgenic rabbits overexpressing VEGFA in the kidney showed significant glomerular damage after 20 weeks and glomerulosclerosis and renal fibrosis after 55 weeks." (PMID 37511521, 2023).
injury (43 papers, 2006 to 2026). Damage inflicted on the body as the direct or indirect result of an external force, with or without disruption of structural continuity. "Application of VEGFA and more specifically its VEGF165 splice variant was shown to stimulate angiogenesis after CNS trauma in brain and spinal cord." (PMID 25386118, 2014). "The opposing functions of VEGFA and SEMA3s on ECs may limit the endogenous angiogenic capacities after CNS trauma." (PMID 25386118, 2014). "Vascular endothelial growth factor-A (VEGF-A) is an important modulator of vascular health and VEGF-A promotes the brain’s ability to recover after more severe forms of brain injury; however, the role of VEGF-A in mTBI remains poorly understood." (PMID 37933736, 2024). "In the ischemic brain, VEGFA-mediated neuroprotective effects preceded any signs of angiogenesis or neurogenesis, and in traumatic brain injury models, VEGFA reduced hippocampal neuronal apoptosis without influencing neuronal proliferation." (PMID 40050849, 2025).
metastatic carcinoma (43 papers, 1997 to 2025). A carcinoma which has spread from the original site of growth to another anatomic site. "Bevacizumab, a monoclonal antibody targeting VEGFA, can inhibit vascular endothelial growth factors and can be used to treat various metastatic cancers." (PMID 35464051, 2022). "It was evaluated in clinical studies with various advanced or metastatic cancer patients, often in combination with bevacizumab which inhibits the vascular endothelial growth factor A (VEGFa)." (PMID 32365809, 2020). "Bevacizumab (Avastin) is another monoclonal antibody that hinders vascular endothelial growth factor-A (VEGF-A) which has been reported to be involved in certain metastatic cancers." (PMID 29484148, 2018). "However, unlike decorin, endorepellin, endostatin and biglycan foster tumour angiogenesis in metastatic cancer via upregulating VEGFA levels and VEGFA–VEGFR2 signalling." (PMID 34982945, 2022).
neuropathy (43 papers, 2014 to 2026). A disorder affecting the nervous system that manifests with pain, tingling, numbness, and/or muscle weakness. "In this context, the vascular endothelial growth factor A (VEGF-A) has emerged as a candidate neuropathy hallmark and its decrease has been related to pain relief." (PMID 34649573, 2021).
thrombosis (43 papers, 2011 to 2025). "The subjects with the VEGFA rs3025039 TT genotype had a higher risk of deep vein thrombosis in typical sites." (PMID 34440447, 2021). "In a recent study, RNA sequencing in granulocytes of PV patients documented higher expression levels of F3, SELP, VEGFA, and SLC2A1, that were directly correlated with JAK2 expression and JAK2V617F allele burden in patients with a history of thrombosis." (PMID 34897288, 2021). "Current knowledge about the potential impact of the rs3025039 SNV in VEGFA on angiogenesis and endothelial function is still very limited; thus, the explanation for the observed relationship with thrombosis remains highly speculative." (PMID 34440447, 2021). "In conclusion, in subjects with PMF, the VEGFA rs3025039 CT or TT genotypes are more common in those with JAK2V617F than in those without JAK2V67F mutation and are associated with disease severity, poor prognosis, and risk of deep vein thrombosis." (PMID 34440447, 2021). "It has been shown that vascular endothelial growth factor A (VEGFA) and angiotensin-converting enzyme (ACE) are upregulated in the corpus cavernosum of diabetic rats, and these proteins can promote the generation of mucosal blood vessels and increase the risk of vascular thrombosis." (PMID 36210810, 2022).
skin cancer (42 papers, 2006 to 2025). "Elevated VEGFA levels are associated with several pathological conditions, including chronic inflammatory skin diseases and various types of skin cancers." (PMID 35956111, 2022). "Elevated levels of VEGFA are associated with several pathological conditions, including chronic inflammatory skin diseases and several types of skin cancer." (PMID 23166713, 2012). "However, hsa-miR-361-5p was identified to be a regulator of VEGFA and thus associated with skin cancer." (PMID 25175044, 2014). "In skin cancer, VEGFA promotes macrophage recruitment to the tumor and thereby facilitates tumor-associated macrophage development." (PMID 32616068, 2020). "For instance, M2-derived vascular endothelial growth factor-A (VEGF-A) contributes to the neovascularization and inflammatory cell recruitment at tumor sites in a mouse model of skin cancer." (PMID 36741415, 2022). "The NO pathway in the BioCarta includes VEGFA SNPs and plays an important role in the regulation of vascular endothelial function facilitating, in particular, BCC development and an angiogenic response propagated by the growing skin cancer." (PMID 35886018, 2022).
dementia (41 papers, 2009 to 2026). Loss of intellectual abilities interfering with an individual's social and occupational functions. "The biomarker vascular endothelial growth factor-A (VEGF-A) was additionally chosen for all-cause dementia." (PMID 38570813, 2024). "Clinically, higher VEGFA levels have previously been associated with the development of dementia in an elderly population." (PMID 37834363, 2023). "Meanwhile, the reduced expression of the ACOX1 and VEGFA genes showed a prognostic value in the risk of MCI and dementia." (PMID 39125683, 2024). "A comparative analysis of gene expression in MRI type 1 CSVD patients with clinically significant CI (mild CI (MCI) and dementia) and the control group showed a decrease in the VEGFA gene (p = 0.034) in patients with CI." (PMID 39125683, 2024). "In a comparative analysis of gene expression in MRI type 2, we found a decrease in the expression of ACOX1, BIN1, CD2AP, CD33, TNFR1, VEGFA, and VEGFC genes in clinically significant CI (MCI and dementia) compared to the control group." (PMID 39125683, 2024). "Indeed, twenty of the differentially expressed proteins in dementia compared with MCI were enriched in the pathways regulating angiogenesis and involved in the VEGFA–VEGFR2 signaling pathway, including the placental growth factor (PGF)." (PMID 37175824, 2023).
ischemic disease (41 papers, 2010 to 2025). Lack of blood supply to an area of the body, resulting in impairment of tissue oxygenation. "The most widely studied VEGF family, especially VEGFA, is a key angiogenic factor regulating ischemic diseases." (PMID 35937999, 2022). "Vascular endothelial growth factor A (VEGF-A) is a key regulator of blood vessel formation and maintenance making it a promising therapeutic target for activation in ischemic diseases." (PMID 30463374, 2018).
cerebral edema (40 papers, 2005 to 2025). "Bevacizumab has been proposed as an alternative to dexamethasone for combatting cerebral edema as it specifically targets vascular endothelial growth factor A (VEGF-A) which promotes both angiogenesis and vascular permeability." (PMID 34041034, 2021). "Especially, in high altitude cerebral edema (HACE) proinflammatory cytokines like IL-1β, IL-6, or vascular endothelial growth factor A (VEGF-A) are believed to play an important role." (PMID 32033172, 2020).
cognitive decline (40 papers, 2014 to 2026). "Regarding the study of VEGFA in AD, higher-baseline CSF VEGFA levels are associated with slower rates of hippocampal atrophy and slower rates of cognitive decline, particularly among individuals with elevated levels of AD biomarkers." (PMID 37999404, 2023). "Some studies have found that reduced levels of VEGFA protein in the serum and cerebrospinal fluid are associated with an increased risk of AD and cognitive decline." (PMID 35529440, 2022). "For example, work from our group has indicated that higher-baseline CSF VEGFA levels are associated with slower rates of hippocampal atrophy and slower rates of cognitive decline, particularly among individuals with elevated levels of AD biomarkers." (PMID 31332262, 2021). "Moreover, higher concentrations of VEGFA in cerebrospinal fluid were found to be associated with slower rates of hippocampal atrophy and cognitive decline, particularly in AD biomarker-positive adults." (PMID 37927608, 2023). "It has been observed that overexpression of this miRNA reduces the levels of VEGFA, a factor known for its protective effects against cognitive decline in patients with AD." (PMID 39766348, 2024). "As a blood-borne factor, vascular endothelial growth factor-A (VEGF-A) signaling has been shown to be involved in halting AD-related neurodegeneration and cognitive decline." (PMID 37280283, 2023). "Like in serum and the placenta of preE patients with impaired placental angiogenesis, decreased VEGFA (the most well-studied ligand of the family) in serum and cerebrospinal fluid (CSF) is associated with a greater risk of AD and cognitive decline, although not without contrasting opinions." (PMID 39857613, 2024).
pituitary adenomas (40 papers, 2008 to 2026). "In pituitary adenomas, vascular endothelial growth factor A promotes cancer cell migration and angiogenesis." (PMID 41551914, 2026). "RSUME (RWD‐containing sumoylation enhancer) plays an important role in pituitary adenoma invasion by stabilizing hypoxic‐inducing factor‐1α and promoting VEGFA expression." (PMID 38738958, 2024). "The expression of VEGFA obviously increased in pituitary adenoma with extrasellar growth than that in intrasellar ones, suggesting VEGFA could be markers for poor outcome after tumor resection." (PMID 28163656, 2017). "Furthermore, VEGFA expression was related to invasion of pituitary adenoma." (PMID 28163656, 2017).
autoimmune disease (39 papers, 2009 to 2025). A disorder resulting from loss of function or tissue destruction of an organ or multiple organs, arising from humoral or cellular immune responses of the individual to their own tissue constituents. "Genes related to these autoimmune diseases and Th17 cell differentiation, including CTLA4, IFN-ALPHA-8, IL12RB2, TRAV3, TRAV16, FOS, and VEGFA, were up-regulated in the E. coli group but down-regulated in the BL + E." (PMID 39707535, 2024). "Given that VEGFA, IL2, and MPO all play roles in autoimmune diseases, in this study, kaempferol has been shown to bind well with these molecules, which suggests a potential avenue for therapeutic interventions targeted at these molecular interactions in the context of vitiligo." (PMID 38659590, 2024).
cyst (38 papers, 2010 to 2024). A sac-like closed membranous structure that may be empty or contain fluid or amorphous material. "In contrast, the SCA biomarker VEGFA was highly expressed in cyst fluid and plasma." (PMID 37414831, 2023). "More interestingly, we found that cyst fluid and high iron consistently upregulated the expression of IL8 and VEGFA and downregulated the expression of TNFα and CCL2 inTHP-1 cells." (PMID 36547083, 2022). "A similar result in our study has shown that cyst fluid and iron-induced ferroptosis can up-regulate IL8 and VEGFA expression in THP-1 cells." (PMID 36547083, 2022). "Collectively, our study reveals that ferroptosis triggered by high iron in cyst fluid promotes the development of EMs by impairing macrophage phagocytosis and producing more angiogenic cytokines (e.g., IL8 and VEGFA)." (PMID 36547083, 2022). "The results showed that VEGFA and VEGFR2 were mainly expressed in the fibrous endothelial cell infiltration area between the outer cyst wall and the liver cells and the inner cyst wall of multilocular echinococcosis, which also indicate that neovascularization may occur in these two areas." (PMID 39619441, 2024). "High VEGFA may contribute to the occurrence of PCOS by excess angiogenesis; inhibition of VEGFA in the rat ovaries of a PCOS model partially restored the accumulation of the small follicles observed, and reduced cyst formation, consequently improving ovulation and follicular development." (PMID 34360981, 2021).
multiple sclerosis (37 papers, 2008 to 2026). A progressive autoimmune disorder affecting the central nervous system resulting in demyelination. "Inactivation of VEGFA in astrocytes leads to BBB disruption in multiple sclerosis models." (PMID 41543887, 2026).
pterygium (37 papers, 2011 to 2026). A wedge-shaped fibrovascular lesion arising from the bulbar conjunctiva and extending to the cornea. "Results support the involvement of FGF2 and VEGFA in pterygium pathogenesis and imply that pharmacological modification of the clinical behavior of pterygium may be possible with agents directed against specific growth factors, such as VEGFA." (PMID 23432803, 2013). "Furthermore, FGF2 and VEGFA expression was significantly higher in more advanced pterygium, compared with less advanced ones, whereas VEGFA was also significantly correlated with postoperative recurrence." (PMID 23432803, 2013). "Perplexingly, while molecular markers indicate that our pterygium specimens were not vascularized, expression of several regulators of angiogenesis was elevated, including VEGFA." (PMID 34769520, 2021).
uveal melanoma (37 papers, 2008 to 2025). A melanoma derived from melanocytes of the uveal tract. "Next, we tested the involvement of chemokines CXC11 and CCL18 as well as VEGFA as they were found involved in uveal melanoma recruitment of tumor-associated microphages and angiogenesis." (PMID 32756477, 2020). "In human uveal melanoma (UM), tumor enlargement is associated with increases in aqueous humor vascular endothelial growth factor-A (VEGF-A) content that induce neovascularization." (PMID 30483120, 2018).
aneurysm (36 papers, 2016 to 2025). Bulging or ballooning in an area of an artery secondary to arterial wall weakening. "Promotes endothelialization and facilitates the vascular repair of aneurysms via PTEN-mediated PI3K/AKT/VEGFA pathway." (PMID 40565557, 2025). "What is known is that miR-17-5p is commonly associated with the regulation of oncogenes from the PI3K/AKT signaling pathway facilitating even the vascular repair process after aneurysms in a PI3K/AKT/VEGFA pathway dependent manner." (PMID 35806488, 2022). "This repression leads to increased VEGFA expression, resulting in endothelial cell proliferation, enhanced migration, suppressed apoptosis, and increased vascular permeability, all processes critical to aneurysm growth and rupture." (PMID 41342741, 2025). "Moreover, increased VEGF has been associated with abdominal aneurysm in patients, and inhibition of VEGFA suppressed aneurysm formation in a mouse model." (PMID 41056017, 2025). "Taken together, higher MLDGS score may represent higher expression of IL1B, TLR4, VEGFA and MMP2, and lower expression of NOS3, implying inferior vascular stability at the molecular level and high risk of aneurysm rupture and CVS onset." (PMID 36844725, 2023).
renal failure (36 papers, 2009 to 2025). "Relevant literature have shown that IL6, AKT1, VEGFA, FN1, TIMP1, ALB and TNF are associated with renal insufficiency." (PMID 36209090, 2022). "Elevation in VEGFA and CD28 in patients with kidney failure suggests its involvement in the emergence of this organ failure." (PMID 34177897, 2021).
Thrombocytopenia (36 papers, 2012 to 2025). A reduction in the number of circulating thrombocytes. "Clinical symptoms of Crimean-Congo haemorrhagic fever (CCHF) include acute viral fever, ecchymosis, and thrombocytopenia, and a recent study showed significantly increased VEGFA levels in patients with CCHF." (PMID 30849965, 2019). "This may indicate compensatory activation of VEGFA transcription in BM stromal cells depending on the severity of thrombocytopenia and should be further investigated." (PMID 39594656, 2024).
diabetic foot ulcers (35 papers, 2015 to 2026). "In patients with diabetic foot ulcers, the VEGFA concentration was reduced in the case of the CC genotype." (PMID 38139123, 2023). "Thus, in current study, we profiled the miRNAs in EVs derived from wound fluids of diabetic foot ulcers (DF-EVs) and nondiabetic wounds (Control-EVs) and found that miR-195-5p and miR-205-5p, which can regulate VEGFA expression, were upregulated in DFs." (PMID 34370714, 2021).
Peritoneal Fibrosis (35 papers, 2014 to 2025). Disorder characterized by a wide range of structural changes in PERITONEUM, resulting from fibrogenic or inflammatory processes. "Targeting the ESR1/H19/VEGFA pathway pharmacologically can attenuate high glucose-induced peritoneal fibrosis." (PMID 40918510, 2025). "VEGFA is an important cytokine contributing to ultrafiltration failure in peritoneal dialysis fibrosis, which leads to pathological proliferation of peritoneal vessels as well as peritoneal fibrosis with reduced osmotic pressure in the clinic." (PMID 37697303, 2023). "Thus, VEGFA plays a vital role in the deterioration of peritoneal fibrosis by promoting MMT of peritoneal cells and angiogenesis and has become a target for easing PD-related fibrosis." (PMID 37697303, 2023).
retinal degeneration (35 papers, 2009 to 2025). Degeneration of the retina. "The development of AMD is associated with CFH (an inhibitor for alternative complement), EFEMP1 (a high-risk gene for AMD and other retinal degenerations), and VEGFA (a protein associated with increased choroidal neovascularization)." (PMID 36078063, 2022). "VEGFA and FLT1 targeted therapies are being explored as both pro- and anti-angiogenic therapies for several indications including retinal degeneration, cancer, pre-eclampsia, and neuromuscular diseases." (PMID 38842166, 2024).